AGRN (agrin)
Diseases named in the same sentence as AGRN in open-access papers (continued):
Sharing a sentence is not in itself a finding about the gene and the disease.
tumor (54 papers, 2010 to 2026). "A suboptimal dose for VT107 (10 mg kg−1) was not sufficient to completely reduce agrin levels; however, when used with osimertinib, the combination strikingly reduced agrin, which was associated with a lower tumor burden." (PMID 40165020, 2025). "Agrin expression was notably linked to tumor size and metastasis, suggesting its involvement in tumor growth and migration." (PMID 39123447, 2024). "AGRN is a gene known for its tissue-specific isoform expression and has recently been implicated in the Hippo pathway in the tumor microenvironment in several cancer types." (PMID 39595158, 2024). "Agrin expression exhibited a significant association with tumor size (p = 0.041) and metastasis (p = 0.034), suggesting its involvement in tumor growth and dissemination." (PMID 39123447, 2024). "Analysis of tumor immune cell infiltration revealed that AGRN is closely associated with memory CD4+T cells activated, monocytes, plasma cells, Tfh cells, NK cells activated, mast cells resting, and DCs resting." (PMID 37841281, 2023). "We hypothesized that the discrepancy between these in vitro and in vivo work could be attributed to the availability of agrin from the localized or metastasized tumor that might rescue the loss of agrin in ECs of the EC-agrncKO mice during tumor angiogenesis." (PMID 35174224, 2021). "Collectively, our data indicated that endothelial agrin was not required for EC recruitment during the early stages of localized and metastatic tumor growth in vivo as the endothelial loss of agrin could be compensated by the tumor-derived agrin." (PMID 35174224, 2021). "Taken together, these data suggested that endothelial agrin was not required for EC recruitment during the early stages of localized and metastatic tumor growth in vivo as agrin derived from the tumor could compensate for the loss of endothelial agrin." (PMID 35174224, 2021). "Clearly, proof-of-principle studies have shown that antibodies directed against agrin may have in vivo tumor-inhibitory capabilities, although the underlying mechanism of action needs to be defined." (PMID 29415512, 2018). "Conversely, agrin processing products like the C-terminal fragment identified in this study as a tumor-associated antigen may be released into the circulation." (PMID 20184735, 2010). "Ligand-receptor pairs linked to high-risk tumors, including IL1A_IL1RAP, COL5A1_ITGB1, APP_NCSTN, PLAU_ITGA5, AGRN_ITGB1, and LAMC2_ITGA6, were found to be particularly enriched in tumor regions." (PMID 40021759, 2025). "Silencing agrin expression significantly impairs cancer cell behaviors such as movement, growth, invasion, and the formation of colonies and tumor spheroids, highlighting its pathological importance in OSCC progression." (PMID 40299352, 2025). "Agrin promotes immune evasion and tumor growth by stimulating regulatory T-cells and increasing interleukin-6 secretion." (PMID 40584122, 2025). "In conclusion, we reveal that agrin serves as a mechanosensing ECM protein for EGFR toward tumor stiffness." (PMID 40165020, 2025). "Subsequent AGRN knockout experiments in a laboratory setting demonstrated a marked reduction in tumour proliferation, migration and invasion capabilities." (PMID 39183444, 2024). "Future research will focus on exploring the molecular pathways through which agrin exerts its effects on tumor growth and metastasis." (PMID 39123447, 2024). "Our previous studies demonstrated that agrin levels are significantly elevated in HCC tumor tissues and the serum of HCC patients, while low levels were observed in normal livers." (PMID 39123447, 2024). "From a therapeutic perspective, our previous work has demonstrated that antibodies targeting agrin reduced oncogenic signaling and tumor growth in vivo, highlighting agrin’s potential as a therapeutic target for antibody therapy in HCC." (PMID 39123447, 2024).
tumor (continued). "The results showed that AGRN’s expression level varied according to distinct tumor types and was closely correlated with some tumor patients’ prognosis, immune cell infiltration, and other indicators." (PMID 37841281, 2023). "AGRN was identified in TCGA data as highly expressed in 18 tumor tissues and lowly expressed in KICH." (PMID 37841281, 2023). "Recent research has shown that AGRN is upregulated in various tumor tissues, and plays an important role in regulating malignancy development and immune microenvironment." (PMID 37841281, 2023). "Our research indicates that AGRN expression is significantly higher in the majority of tumor tissues." (PMID 37841281, 2023). "Three heparan sulfate proteoglycan (HSPG) core proteins were identified to be differentially expressed between adjacent normal and tumor tissue regions: agrin, perlecan, and collagen alpha-1 (VIII) chain." (PMID 37069213, 2023). "By analyzing the correlation between AGRN expression and immune cell infiltration in tumor tissues, we found that AGRN expression correlated higher with immune cell infiltration in LAML, TGCT, PAAD, THYM, GBM, KIRP, and LIHC tissues." (PMID 37841281, 2023). "Downregulation of AGRN in CSCs and in CSCs extracellular vesicles reduces tumor growth, and the use of a neutralizing anti-human AGRN antibody also reduces cell growth, as well as the activation of YAP." (PMID 36358747, 2022). "Glypican-3 is a cell membrane-anchored proteoglycan, while agrin is present in the basement membranes of tumor vasculature, bile ducts, and the portal area." (PMID 35186754, 2022). "During cancer progression, Agrin-bound LRP4 associates instead with β1 integrins and elicits FAK signaling that in turn fosters tumor angiogenesis and growth by stabilizing VEGFR-2 protein levels in ECs74." (PMID 34131655, 2021). "Our results indicated that Agrin promotes tumor cell growth and Treg infiltration via increasing IL-6 expression and secretion through PI3K/AKT pathway in NSCLC." (PMID 35111682, 2021). "In the xenograft tumor model using BALB/C nude mice, Agrin deficiency significantly suppressed NSCLC cell growth in vivo." (PMID 35111682, 2021). "Nevertheless, these experiments cannot clearly address the role of endothelial agrin in tumor angiogenesis as the recipient's tumor infiltrating ECs are not deficient in agrin." (PMID 35174224, 2021). "Agrin influences tumor cell migration, adhesion and resistance to chemotherapy impacting on FAK, ERK and cyclin D1 activation." (PMID 34199373, 2021). "The IHC results indicated that Agrin and pAKT expression were obviously higher in tumor than adjacent normal tissues." (PMID 35111682, 2021). "This study examined the effects and the underlying mechanisms of Agrin in NSCLC and tumor-infiltrated immune cells." (PMID 35111682, 2021). "The expression levels of Agrin were higher in the NSCLC tumor samples (510 cases) than the adjacent normal tissues (59 cases, P < 0.001)." (PMID 35111682, 2021). "Tumor xenograft mouse model was used to confirm the effects of Agrin on NSCLC growth and tumor-infiltrated regulatory T cells (Tregs) in vivo." (PMID 35111682, 2021). "Agrin levels in NSCLC cells were closely related to tumor progression and metastasis, and its function was enriched in the PI3K/AKT pathway." (PMID 35111682, 2021). "Agrin enhanced tumor growth and invasion through PI3K/AKT pathway, and induced IL-6 expression and secretion in NSCLC cells to promote Treg differentiation." (PMID 35111682, 2021). "An increase in agrin has been demonstrated in cancerous cells, and studies using experimental models have shown that addition of agrin promotes cancer whilst agrin depletion slows tumor growth." (PMID 32612983, 2020). "Knock-down of agrin, on the contrary, reduces both the primary and the metastatic tumor load in vivo." (PMID 33330449, 2020).
tumor (continued). "As a consequence, agrin depletion impedes cell adhesion and invasion and has a dramatic effect on tumor growth, practically eliminating tumors completely." (PMID 33330449, 2020). "Many oncogenic and tumor suppressive factors, such as Agrin, Rab7, AKT/mTOR pathway, STAT3, and transcription-3 signalling have been identified for HCC." (PMID 31164410, 2019). "In orthotopic model, agrin silencing reduces tumour aggressiveness, like vascular and neural invasion." (PMID 29872149, 2018). "Tumours generated from control cells show significantly greater aggressiveness in comparison to tumours originating from agrin-silenced cells." (PMID 29872149, 2018). "Further, we show that agrin silencing interferes with cancer cell motility, proliferation, invasion, colony and tumour spheroid formation, and it also reduces the phosphorylation of FAK, ERK and cyclin D1 proteins in OSCC cells." (PMID 29872149, 2018). "A working model is that agrin antagonizes the tumor-suppressive functions of Merlin and LATS1/2 kinase by regulating the cell-matrix adhesions." (PMID 29415512, 2018). "During this process, agrin inhibited the Hippo tumor suppressor pathway leading to enhanced activity of YAP." (PMID 29415512, 2018). "To establish that Agrin-mediated regulation of FAs affects tumour cell growth, we used FAK inhibitor PF-562271 that reduced pFAK activity and spheroid culture diameter in a dose-responsive manner." (PMID 25630468, 2015). "Western blot analysis revealed reduced levels of Ki67, pY397FAK, pAkt and vimentin but increased levels of cleaved caspase-3 in Agrin-depleted tumours." (PMID 25630468, 2015). "Low Agrin expression in normal livers and the observation that Agrin antibodies reduced pre-established tumour growth offer the possibility of Agrin as a potential therapeutic target by antibody therapy." (PMID 25630468, 2015). "Agrin depletion hampered oncogenic signalling and tumour growth in xenograft and orthotopic models that is rescued by Agrin re-expression or addition of soluble Agrin, suggesting the tumour initiating and maintenance properties of Agrin." (PMID 25630468, 2015). "From these studies, we know that extracellular matrix molecules within the tumor like agrin and its receptor alpha-dystroglycan are involved in forming orthogonal arrays of particles." (PMID 26115524, 2015). "The reduction in proliferation, blood vessel number, tumor‐fenestrated collagen, and nuclear YAP/TAZ was consistent with agrin loss in PDX#20 in response to the combination therapy, while no major differences amongst the non‐responsive PDX#18 tumors were observed." (PMID 40165020, 2025). "Inhibiting AGRN through small molecules or neutralizing antibodies may help disrupt its role in tumor invasion and metastasis." (PMID 40299352, 2025). "To assess this in a scenario that mimics EGFR‐addicted tumor‐thriving conditions, we silenced agrin in both wild‐type and mutant EGFR (del 19) overexpressing H1299 and implanted them subcutaneously with soft (≈0.5 kPa) or stiff VitroGel RGD (30 kPa) in SCID mice." (PMID 40165020, 2025). "Hence, this molecular bridging function mediated by sAgrin possibly clusters Integrin β1 to EGFR in mechanosensitive adhesion sites in response to increased agrin with tumor stiffness." (PMID 40165020, 2025). "Importantly, antibodies targeting agrin have been shown to reduce oncogenic signaling and tumor growth in vivo, highlighting its potential as a therapeutic target." (PMID 39123447, 2024). "We analyzed the relationship between AGRN expression and the tumor microenvironment." (PMID 37841281, 2023). "AGRN expression levels affect the prognosis of tumor patients." (PMID 37841281, 2023). "In addition, analysis of the normal tissue data downloaded from the GTEx database revealed that AGRN expression was elevated in 28 tumor tissues and weakly expressed in KICH and TGCT." (PMID 37841281, 2023).
tumor (continued). "In addition, we comprehensively analyzed the prognostic value of AGRN in cancer patients and assessed the role of AGRN in tumor microenvironment (TME), tumor mutation burden (TMB), and microsatellite instability (MSI)." (PMID 37841281, 2023). "Multiple HSPGs and CSPGs core proteins and related enzymes were upregulated in GBM tumors relative to normal brain, including various genes previously implicated in tumor invasion and tumorigenesis and observed by the present study, including glypican 1, CSPG4, BGN, and AGRN." (PMID 35202840, 2022). "In fact, the brain, lung, muscle and tumor where agrin expression is detected are highly vascularised tissues; however, the in vivo function of endothelial agrin during development and pathophysiological angiogenesis remains unclear." (PMID 35174224, 2021). "In the group of PBMC injection, Agrin knockdown also inhibited tumor growth." (PMID 35111682, 2021). "Because of these exemplary roles of Agrin in the tumor and regenerative microenvironments that approximates a wound healing niche, here we show that Agrin tunes a mechanically competent wound microenvironment enforcing skin tissue healing by improving keratinocyte mechanoperception." (PMID 34732729, 2021). "Taken together, our findings may suggest that agrin could play a redundant role in endothelial development, physiological and tumor angiogenesis." (PMID 35174224, 2021). "Agrin contributes to immune synapse information and is involved in tumor metastasis." (PMID 35111682, 2021). "Therefore, the study has elegantly revealed the potential of agrin as a therapeutic target for dampening tumor angiogenesis and metastasis." (PMID 35174224, 2021). "Cumulatively, our findings may suggest that agrin could play a redundant role in endothelial development during physiological and tumor angiogenesis." (PMID 35174224, 2021). "Previous reports show that agrin mediates angiogenesis in the tumor microenvironment." (PMID 35174224, 2021). "Collectively, the prior work suggests that agrin could be an essential target for developing cancer therapy through inhibiting EC proliferation and tumor angiogenesis." (PMID 35174224, 2021). "In a recent study comparing the matrsiome of MDA-WT and MDA-Lung tumour xenografts, MMP1 and THBS2 were detected uniquely in MDA-WT tumours and AGRN was detected uniquely in MDA-Lung tumours, which correlates with our proteomics data of MDA-WT and MDA-Lung secretomes." (PMID 31160380, 2019). "However, to understand how generic is agrin secreted and/or expressed in the liver during its tumor initiation stages would be key for effective HCC therapy." (PMID 29415512, 2018). "Mice that received agrin-silenced cells (shAgrin) developed less aggressive tumours." (PMID 29872149, 2018). "Hence, how agrin-YAP activity contributes towards tumor invasiveness is an issue of outstanding interest that needs to be explored." (PMID 29415512, 2018). "Notably, orthotopic tumours produced by agrin-silenced cells exhibited reduced aggressiveness, showing less vascular and neural invasion, which are associated with a better clinical prognosis." (PMID 29872149, 2018). "Whether agrin plays a role in disorganization of the basement membrane through YAP activation that is important for tumor progression and metastasis is yet to be investigated." (PMID 29415512, 2018). "In subsequent experiments, we investigated whether the silencing of agrin interferes with tumour expansion both in vitro as well as in vivo." (PMID 29872149, 2018). "Furthermore, the in vivo role of Agrin was also investigated in an orthotopic HCC tumour model as tissue microenvironment has a crucial role in carcinogenesis." (PMID 25630468, 2015). "Having mechanistically deciphered the oncogenic properties of Agrin in vitro, we next examined whether silencing Agrin affects tumour development in vivo." (PMID 25630468, 2015). "Agrin-GFP rescued cells have significantly increased in vivo tumour growth." (PMID 25630468, 2015).
tumor (continued). "Furthermore, there was a significantly higher expression of agrin in tumor samples, compared to controls (Mann-Whitney U test, p<0.0005)." (PMID 25506919, 2014). "Overall, our findings opened new avenues to better understand the role of agrin and perlecan, as well as their involvement in carcinogenesis, which may offer a novel approach to cancer therapy by targeting the tumor microenvironment." (PMID 25506919, 2014). "Nevertheless, whether the tumor or EC derived agrin should be targeted in vivo remains unknown." (PMID 35174224, 2021). "Furthermore, we also determined the potential impact from tumor cell derived agrin on tumor angiogenesis by quantifying agrin gene expression in B10F10-Luc cells compared to that of the ECs isolated from EC-agrnfl/fl and EC-agrn+/+ mice by quantitative RT-qPCR." (PMID 35174224, 2021). "Moreover, endothelial loss of agrin in adult mice does not weaken vascular integrity nor vasoreactivity in vivo; and does not inhibit tumor angiogenesis and metastasis." (PMID 35174224, 2021). "In addition, agrin silencing suppresses the colony and tumour spheroid formation." (PMID 29872149, 2018). "Importantly, antibodies targeting Agrin reduced oncogenic signalling and tumour growth in vivo." (PMID 25630468, 2015). "The enhancement of Agrin signal can further change the matrix structure of TME and provide support for tumor cell attachment and invasion." (PMID 40932351, 2026). "In contrast, the tumor growth from shControl wild‐type and mutant EGFR overexpressing cells supported by stiff VitroGel were significantly reduced upon agrin silencing." (PMID 40165020, 2025). "This is the case of KIF23, which was a hub gene in M2-tumor-associated macrophages, and it showed a higher expression level in tumor tissues, similarly to YWHAQ and AGRN." (PMID 40136513, 2025). "Principal component analysis (PCA) illustrated that agrin–EGFR expression along with other YAP/TAZ targets, aligned together in lung tumors distinct from the normal or tumor‐adjacent tissues." (PMID 40165020, 2025). "Here we reveal that EGFR governs tumorigenic agrin expression and then sensitizes the RTK to tumor‐stiffness through integrin mechanosignaling." (PMID 40165020, 2025). "This correlation between agrin and AFP further underscores the complexity of the tumor microenvironment and its impact on biomarker expression." (PMID 39123447, 2024). "Agrin, a secreted heparan sulfate proteoglycan, was found to be significantly overexpressed and secreted in HCC tumor tissues and serum samples compared to normal liver tissues." (PMID 39123447, 2024). "The incoming signals from all tumor cells exhibited pattern 3, including but not limited to CD96, CEACAM, and AGRN signaling pathways." (PMID 39224598, 2024). "Increased expression of TIMP1, MMP1, AGRN, UNC5A, and ADAMTS4 was observed, while the expression of UNC5C, TINAG, SPOCK3, and ITGA7 was reduced in the normal FHC cells compared to the HCT8 tumor cells." (PMID 39011483, 2024). "Transplantation of human cancer cells containing shRNA against agrin expression reduces tumor growth and angiogenesis in vivo as evident by reduced numbers of CD31+ blood vessel within the growing tumor." (PMID 35174224, 2021). "Cell division cycle 5-like protein (CDC5L) is essential for mitotic progression, and its target gene, AGRN, seems to be modulated by NEAT1, yielding this whole pathway critical for tumor growth." (PMID 33917553, 2021). "Agrin actively facilitated the interactions of PAK1 and ILK with Merlin, to inactivate the latter’s tumor suppressive abilities." (PMID 29415512, 2018). "Western blot analysis of matched normal (non-tumour; N) and HCC (liver-tumour; T) specimens revealed a significant upregulation of Agrin (9 out of 11 HCC patients) in cancer." (PMID 25630468, 2015). "Interestingly, PDAC patients with high levels of agrin and low inactive YAP show worse disease-free survival and treatment with anti-agrin significantly impairs tumor progression." (PMID 40771583, 2025).